CPEB3 (cytoplasmic polyadenylation element binding protein 3)
Diseases named in the same sentence as CPEB3 in open-access papers (continued):
Sharing a sentence is not in itself a finding about the gene and the disease.
tumor (41 papers, 2016 to 2025). "CPEB3 is suggested as TSG with implications of regulatory involvement in various pathways associated with tumor progression." (PMID 39696035, 2024). "CPEB3 can disrupt the crosstalk between cancer cells and tumor-associated macrophages through the IL-6R/STAT3 signaling pathway, and thereby inhibit epithelial-mesenchymal transition." (PMID 34879089, 2021). "CPEB3 encodes a sequence-specific RNA-binding protein that was proposed to function as a tumour suppressor by transcriptionally repressing EGFR35,36." (PMID 29089486, 2017). "Furthermore, the ORA results indicated that CPEB3 binders were associated with many tumor-related signaling pathways." (PMID 32968053, 2020). "The expression analysis of pathological stages showed that only FOXO1 expression was significantly associated with tumor stage, while miR-9-5p and CPEB3 gene expression were less associated with clinical stage, implying that FOXO1 may have a potential indicative role in pathological grading." (PMID 35805200, 2022). "Of these TIS genes, only CPEB3 exhibited a decreased expression in both the TIS-high group and paired tumor samples, and an abnormally decreased CPEB3 expression conferred a comparatively worse prognosis, indicating the protective role of CPEB3." (PMID 36458010, 2022). "Gain- and loss-of-function analyses indicated that high expression of miR-9-5p was associated with aggressive tumor phenotypes and poor clinical diagnosis, while FOXO1 and CPEB3 inhibited tumor proliferation." (PMID 35805200, 2022). "Next, qRT-PCR analysis indicated that miR-9-5p expression was significantly decreased in tumor tissues after treatment with the combination of miR-9-5p inhibitor/FOXO1/CPEB3-shRNA (left)." (PMID 35805200, 2022). "Although our study has proposed a novel functional miR-9-5p/FOXO1/CPEB3 FFL in the tumor growth of HCC, more complete studies are needed in future experiments to enhance the validation of the functional role of the FFL." (PMID 35805200, 2022). "Past efforts have demonstrated that miR-9-5p and FOXO1 were involved in the progression of HCC in vivo and CPEB3 silencing increased tumor size and weight in HCC." (PMID 35805200, 2022). "The miR-9-5p/FOXO1/CPEB3 FFL was associated with poor prognosis, and promoted cell growth and tumor progression of HCC in vitro and in vivo." (PMID 35805200, 2022). "In this work, we observed that the tumor-formation ability of the CPEB3 overexpressing cells was reduced in nude mice when compared with control." (PMID 35805200, 2022). "For example, hub node gene CPEB3 has been described as a newly discovered tumor suppressor in HCC, and hub TF FOXO1 was responsible for blocking HCC proliferation." (PMID 35805200, 2022). "According to literature, CPEB1 and CPEB3 act as tumor suppressors, while CPEB2 rather displays oncogenic features; in contrast, CPEB4 remains to be classified into one of these two categories." (PMID 34912244, 2021). "The results confirmed that CPEB3 and ACADL were significantly related to tumor immunity: CPEB3 was related to the content of B cells and neutrophil; ACADL was related to the infiltration of B cells, CD8+ T cells, CD4+ T cells, macrophages, and dendritic cells." (PMID 33719338, 2021). "Thus, CPEB3 mutation may inhibit the growth of tumor cells by increasing CPEB3 expression." (PMID 35087829, 2021). "This CPEB3 down-regulation was accompanied by an increase in p-Akt and EGFR levels and a decrease in p21 levels, assigning a tumor-suppressor role for CPEB3 in a context of HCC." (PMID 34912244, 2021). "This in vivo observation further supported the notion that CPEB3 inhibited hepatocarcinogenesis as well as tumor metastasis." (PMID 32968053, 2020).
tumor (continued). "As expected, we observed that the overexpression of CPEB3 led to the suppression of tumor growth compared to the control group, while knockdown of CPEB3 in LoVo cells promoted tumor growth." (PMID 32653013, 2020). "Cytoplasmic polyadenylation element binding protein 3 (CPEB3) has been shown to exhibit tumor-suppressive role in CRC." (PMID 32653013, 2020). "Meanwhile, decreased expression of CPEB3 mRNA was correlated with the rising grade of tumor malignancy in HCC." (PMID 32968053, 2020). "The clinical significance of CPEB3 expression is demonstrated by close correlations with lymphatic metastasis, distant metastasis, and tumor stage." (PMID 33146632, 2020). "GSEA analysis suggested that CPEB3 binders were enriched in tumor samples compared with normal samples in the GSE14520 dataset." (PMID 32968053, 2020). "Gene set enrichment analysis (GSEA) showed a clear stepwise decrease in average gene expression of the four tumor-related pathways from the control group to CPEB3-overexpressed group." (PMID 33146632, 2020). "The inhibition of CPEB3 on tumor progression and M2-like TAM polarization was confirmed in nude mice." (PMID 32653013, 2020). "Eventually, we confirmed that CPEB3 inhibits tumor progression and M2-like TAM polarization in vivo." (PMID 32653013, 2020). "Post-RNA-binding mechanisms of CPEB3 also remain poorly understood, especially in tumor development." (PMID 33146632, 2020). "Western blot confirmed that lidocaine significantly increased the level of CPEB3 protein in tumor cells (P < 0.05)." (PMID 29850575, 2018). "Gene set enrichment analysis plots suggested that lower expression of CPEB3 resulted in the higher neoplasm histological grade (P = 4.95e − 06)." (PMID 29850575, 2018). "As a result, these findings suggest that miR-107 functionally targets CPEB3 and promotes tumor effects partially through CPEB3." (PMID 26497556, 2016). "Strong CPEB3 staining of tumor cells was observed in 8/10 AII, 19/20 AAIII, 7/7 sGBM and 23/24 pGBM." (PMID 27256982, 2016). "More importantly, CPEB3 was identified as a novel and functional target of miR-107, which acts as a tumor suppressor in HCC." (PMID 26497556, 2016). "As expected, there was a significant increase in tumor size and weight of CPEB3 siRNA groups compared with the NC group." (PMID 26497556, 2016). "Notably, NSUN6 emerged as the most influential protective factor, followed by other tumor‐suppressive genes such as CPEB3, RCL1 and DYRK1A." (PMID 40561176, 2025). "Studies have demonstrated that CPEB3 may act as a tumor suppressor in regulating the proliferation, invasion, and apoptosis of various tumors." (PMID 38632984, 2024). "Similar to in vitro results, animal experiments indicated that miR-9-5p silencing and FOXO1 overexpression could suppress the growth of hepatoma xenografts, while silenced CPEB3 promoted tumor growth in vivo, which was consistent with previous reports for HCC." (PMID 35805200, 2022). "In HCC, circ-ITCH binds to miR-421 to prevent CPEB3 down-regulation and tumor growth." (PMID 35910224, 2022). "The expression of some RBPs (such as XPO5 and CPEB3) showed significant differences between the early stage and the advanced stage, and this difference was consistent with the changing trend between normal tissues and tumor tissues." (PMID 35036125, 2021). "CPEB3 was reported as a tumor suppressor in our previous work." (PMID 34930897, 2021). "Finally, the key tumor suppression axis (hsa_circ_0077210/hsa-miR-92b-3p/CPEB3 and ACADL) was constructed." (PMID 33719338, 2021). "After silencing CPEB3, the growth of tumor cells increases while apoptosis decreases." (PMID 35087829, 2021). "Tumor volume dropped significantly in the CPEB3-overexpressing group compared with control (final volume: 0.155 cm3 vs. 0.543 cm3, P = 0.008), whereas the CPEB3-knockdown group had dramatically larger tumors than control (final volume: 1.338 cm3 vs. 0.592 cm3, P = 0.000)." (PMID 33146632, 2020).
tumor (continued). "This outcome suggests that CPEB3 might be involved in the regulation of several tumor-related pathways relevant to tumor progression." (PMID 33146632, 2020). "Moreover, we testified that linc00968 inhibited the growth and invasion of LUAD cells in vitro and suppressed tumor growth and metastasis in vivo via intervening the miR-9-5p/CPEB3 axis." (PMID 33159015, 2020). "Moreover, IHC staining displayed that CPEB3 level was raised in the linc00968-overexpressing xenograft tumor tissues." (PMID 33159015, 2020). "Among these, Cpeb3 and Gnai3 have proven functionality as tumor suppressors in HCC." (PMID 31470644, 2019). "Furthermore, some microRNAs can promote tumor progression by targeting the CPEB3/estimated glomerular filtration rate (EGFR) axis." (PMID 29850575, 2018). "We also found that CPEB3 was downregulated in neoplasms with higher histological grade." (PMID 29850575, 2018). "Interestingly, expression of CPEB3 positively correlated with tumor progression and malignancy but negatively correlated with protein phosphorylation in the alternatively spliced region." (PMID 27256982, 2016). "Furthermore, our results demonstrated that CPEB3 is a newly discovered tumor suppressor that acts via the EGFR pathway." (PMID 26497556, 2016). "Indeed, CPEB3 expression was low in the TCGA database and clinical tumor tissues." (PMID 38632984, 2024). "In addition, the increased level of cytoplasmic polyadenylation element binding protein 3 (CPEB3) induced by lidocaine might also be a part of LA’s anti-tumor mechanisms, which could be regulated by circ_ITCH/miR-421/CPEB3 axis." (PMID 36713494, 2022). "Considering that 20% of vertebrate transcriptomes are under the control of cytoplasmic polyadenylation, the dysregulation of CPEB3 may alter the translation of a broad range of proteins resulting in the formation of a tumor-promoting environment that contributes to the progression of HCC." (PMID 32968053, 2020). "Thus, the dysregulation of CPEB3 will ultimately make tumor cells more aggressive." (PMID 32968053, 2020). "BRMS1L, CPEB3, KIF3B, NEDD4L, PTPRJ, and RBL2 were significantly downregulated in tumor samples compared to controls." (PMID 40943553, 2025). "Among others, CysGCA 5'-half and LysCTT 3'-tRF were upregulated in the tumor samples, and corresponded to decreased expression of PIK3R1, AKT1, and CPEB3." (PMID 39317063, 2024). "MiR-9-5p had higher expression in tumor tissues compared to adjacent tissues, while FOXO1 and CPEB3 were expressed higher in adjacent tissues." (PMID 35805200, 2022). "Cytoplasmic polyadenylation element binding protein 3 (CPEB3), a RNA binding protein, plays a tumor-suppressive role though regulating the expression of malignant transformation-related genes through post-transcriptional control." (PMID 35910224, 2022). "Most importantly, we demonstrated the existence of miR-9-5p/FOXO1/CPEB3 FFL and validated its regulation role in HCC tumor proliferation in vivo and in vitro." (PMID 35805200, 2022). "Gain- and loss-of-function studies demonstrated that miR-9-5p promotes HCC tumor proliferation, while FOXO1 and CPEB3 inhibit hepatocarcinoma growth." (PMID 35805200, 2022). "Cytoplasmic polyadenylation element-binding protein 3 (CPEB3) is a sequence-specific RBP whose overexpression inhibits the proliferation and migration of tumor cells, which has been proven in many studies." (PMID 34926575, 2021). "We found CPEB3 expression was downregulated in tumor samples from HCC patients, indicating a potential function for CPEB3 in tumorigenesis." (PMID 29850575, 2018). "In the present study, we showed that the overexpression of miR-107 accelerates the tumor progression of HCC in vitro and in vivo through its new target gene, CPEB3." (PMID 26497556, 2016). "CPEB3 has been shown to inhibit the progression of gastrointestinal and hepatic cancers by regulating mRNA translation, whereas RCL1 is suggested to act as a tumor suppressor via ribosome biogenesis modulation." (PMID 40561176, 2025).
tumor (continued). "CPEB3 is a crucial modulator of cytoplasmic polyadenylation and was downregulated in colorectal cancer (CRC) and ovarian clear cell adenocarcinoma; therefore, it is considered to be a tumor suppressor." (PMID 33506034, 2021). "NRF3 induces the gene expression of POMP for 20S proteasome assembly and CPEB3 for NRF1 translational repression, inhibiting tumor suppression responses, including cell-cycle arrest and apoptosis, with resistance to a proteasome inhibitor anticancer agent bortezomib." (PMID 34884489, 2021). "The expressions of CPEB3 and ACADL were downregulated in tumor tissues." (PMID 33719338, 2021). "ZHFX3, BIRC6, Axin2, CPEB3 and TPR can regulate the proliferation and apoptosis of tumor cells." (PMID 35087829, 2021). "We identified that FOXO1 directly regulates CPEB3 transcription by ChIP-Seq assays, Western blot and luciferase reporter in HepG2 cells, although the regulation was not significant in Bel7402 cells and tumor tissues (right)." (PMID 35805200, 2022). "However, tumors grew faster when CPEB3 was silenced and the tumor-promoting action was not suppressed by miR-9-5p silencing and FOXO1 overexpression." (PMID 35805200, 2022). "In fact, the low expression of CPEB3 and ACADL could be associated with higher tumor grade but could not be associated with gender, tumor stage, or TNM." (PMID 33719338, 2021). "In addition, compared with control group (normal tumor cells) and negative control group (scramble shRNA), mRNA expression of CPEB3 was demonstrated to be downregulated following transfection with E. coli TOP10-EGFP-shRNA-CPEB3 even after lidocaine treatment." (PMID 29850575, 2018).
cancer (28 papers, 2016 to 2025). A tumor composed of atypical neoplastic, often pleomorphic cells that invade other tissues. "If the NRF3 gene is deficient, NRF1 escapes from CPEB3-mediated translational repression, and complementarily plays a transcriptional role for the robust maintenance of basal proteasome activity in cancer cells." (PMID 34884489, 2021). "Finally, CPEB3 prevented secretion of CCL2 molecules in cancer cells and caused a reversion of the polarity of M2 macrophages." (PMID 34944712, 2021). "In addition, CPEB3 is associated with a gene cluster and signal pathways critical to cancer proliferation and metastasis, such as cellular protein metabolism, cell cycle (cyclins) and cellular stress response (autophagy-related factors, signal transducers and modulators)." (PMID 33146632, 2020). "However, whether the CPEB3-controlled post-transcriptional machinery implicated in cancer progression is poorly explored." (PMID 32968053, 2020). "We found a significant correlation between CPEB3 and B cells, T cells, T helper cells, and Tcm cells, and these immune cells are crucial players in cancer control." (PMID 33506034, 2021). "Impressively, ORA enrichment analyses showed that CPEB3 binders in HCC were enriched in cancer-related pathways, including hippo signaling, ERK signaling, TGF-β signaling, FoxO signaling, and cell senescence." (PMID 32968053, 2020). "We have also revealed NRF3 translationally represses NRF1 by inducing the CPEB3 gene, which maintains basal proteasome activity in cancer." (PMID 32962187, 2020). "Bioinformatic analysis indicates that CPEB3 binders are closely related to cancer progression, especially HCC metastasis." (PMID 32968053, 2020). "In addition, CPEB3 binders were enriched in bicellular junctions, focal adhesions, and cell-substrate adherens junctions, all of which are tightly related to cancer cell metastasis." (PMID 32968053, 2020). "However, we know considerably less about CPEB3’s role in cancer development compared with the body of work available for CPEB1 and CPEB4." (PMID 33146632, 2020). "According to the analysis of The Cancer Genome Atlas (TCGA) database, overexpression of CPEB3 remarkably suppressed a series of signal pathways including several key carcinoma molecular pathways, such as cell adhesion, apoptosis, JAK/STAT signaling, Toll-Like-receptor signaling and so on." (PMID 33146632, 2020). "As the number of known biological functions of CPEBs is growing (cell senescence and cancer, synaptic plasticity, transcriptional regulation), the potential regulatory mechanisms involving CPEB3 may be biologically highly relevant." (PMID 26915047, 2016). "Moreover, the finding also raises the possibility that NRF3 enhances tumorigenesis and malignant transformation by regulating the translation of cancer-related genes via induction of CPEB3 gene expression, although the whole set of CPEB3 target genes remains uncharacterized." (PMID 32962187, 2020). "However, the contribution of CPEB3 to malignant development in cancers is poorly understood." (PMID 33146632, 2020). "However, as few preliminary cancer studies focus on CPEB3, many questions remain unanswered." (PMID 33146632, 2020). "However, few studies have addressed the biological function of CPEB3 in cancer." (PMID 26497556, 2016). "EGFR is correlated with poor prognosis, and cancer metastasis in different cancers including HCC, and it was negatively regulated by CPEB3 in HCC." (PMID 35805200, 2022). "In cancer cells, NRF3 has also been shown to suppress NRF1 translation through the cytoplasmic polyadenylation element binding protein 3 (CPEB3)." (PMID 36359002, 2022). "This review first introduces that NRF3 promotes cancer development through proteasome regulation, by inducing the gene regulation of proteasome maturation protein (POMP) and cytoplasmic polyadenylation element-binding protein 3 (CPEB3)." (PMID 34884489, 2021).
cancer (continued). "CPEB3, GHR, GSTZ1, and KLF8 were especially crucial molecules in the onset and progression of diseases and have been widely investigated in HCC or other forms of malignant tumors." (PMID 36827016, 2023). "Fifty of fusion genes have been reported and 14 involving known cancer genes (ALDH2-ACAD10, BIRC6-SPAST, BIRC6-TTC27, CGNL1-TCF12, CPEB3-IDE, CTNNA1-KDM3B, DNAJB1-PRKACA, LRP5-CHKA, PPFIBP1-STK38L, RNF213-SLC26A11, RXRA-WDR5, SEC16A-NOTCH1, WNK1-ERC1, and ACVR1B-ACVRL1)." (PMID 37403120, 2023). "Our study identified for the first time the existence of miR-9-5p/FOXO1/CPEB3 FFL and revealed its regulatory role in HCC progression, which may represent a new potential target for cancer therapy." (PMID 35805200, 2022). "Higher CPEB3/NRF3 expression, but not higher CPEB3/NRF1 expression, is associated with poor prognosis of cancer patients." (PMID 34884489, 2021). "To evaluate how CPEB3 in CRC cells may inhibit M2-like TAM polarization, we first assessed the expression of CPEB3, CD86 and CD163 in 82 pairs of CRC tissues and adjacent non-cancer tissues using qRT-PCR." (PMID 32653013, 2020). "Although CPEB3 has been mentioned in several studies, no direct functional study on its role in cancer has been performed." (PMID 26497556, 2016). "Furthermore, we identified cancer-related genes aberrantly expressed in ccRCC (BRMS1L, CPEB3, DNAJB9, KIF3B, NFIB, PTPRJ, RBL2) and targeted by members of the miR-106b-25 cluster, suggesting that their dysregulation may be driven by these miRNAs." (PMID 40943553, 2025). "Consequently, CPEB3 and ACADL might inhibit the occurrence of HCC through inhibiting a variety of cancer signaling pathways related to tumorigenesis and progression." (PMID 33719338, 2021). "Similarly, the levels of CPEB3 were downregulated in LUAD tissues than in para-carcinoma tissues, resulting in a positive correlation between linc00968 and CPEB3, and a negative relationship between miR-9-5p and CPEB3." (PMID 33159015, 2020).
digestive tumor (2 papers, 2022 to 2025). "CPEB3 encodes an RNA‐binding protein that regulates mRNA translation through multiple mechanisms and has been implicated in gastrointestinal tumors." (PMID 40561176, 2025).